MIR548AA2 (microRNA 548aa-2)
Synonyms: hsa-mir-548aa-2
Gene: MicroRNA gene on chromosome 17 (67,471,489 to 67,471,585, forward strand). Ensembl gene ENSG00000207688.
Gene Ontology:
Biological process: miRNA-mediated post-transcriptional gene silencing
Cellular component: RISC complex